GABARAPL3 (GABA type A receptor associated protein like 3 (pseudogene))
Description:
Ubiquitin-like modifier involved in autophagosome formation. Whereas LC3s are involved in elongation of the phagophore membrane, the GABARAP/GATE-16 subfamily is essential for a later stage in autophagosome maturation (By similarity).
Synonyms: ATG8D
Gene: Transcribed processed pseudogene on chromosome 15 (90,348,844 to 90,349,197, reverse strand). Ensembl gene ENSG00000238244.
Subcellular location: Cytoplasm, cytoskeleton; Cytoplasmic vesicle, autophagosome membrane
Diseases named in the same sentence as GABARAPL3 in open-access papers:
GABARAPL3 is named in the same sentence as 3 diseases in open-access papers, as found by Europe PMC text mining. Sharing a sentence is not in itself a finding about the gene and the disease. The quoted sentences say what the papers report.
diffuse gastric adenocarcinoma (1 paper, 2021). An adenocarcinoma arising from the stomach. "Four DEGs including ATG10, ATG16L2, ULK4 and GABARAPL1 showed differences in diffuse gastric adenocarcinoma subgroup, while other four DEGs including ATG7 (probe 224025_s_at), GABARAPL1, WIPI2 and GABARAPL3 showed differences in gastric intestinal type adenocarcinoma subgroup." (PMID 33604190, 2021).
GABARAPL3 also shares sentences with these, for which no sentence is quoted: gastric intestinal type adenocarcinoma (1 paper); tumour (1).